SDC1 (syndecan 1)
Diseases named in the same sentence as SDC1 in open-access papers (continued):
Sharing a sentence is not in itself a finding about the gene and the disease.
myeloma (continued). "Evaluation of SDC1 levels in the bone marrow of multiple myeloma patients showed much higher levels than circulating SDC1 levels in peripheral blood." (PMID 26293675, 2015). "For example, the binding of HGF with SDC1 enhances downstream signaling in myeloma cells, osteoblasts, and stromal cells." (PMID 26293675, 2015). "Increased levels of shed syndecan-1 in serum correlate to tumor burden and poor outcome in multiple myeloma." (PMID 26420915, 2015). "For example, syndecan-1 expression and its shedding from the cell surface appear to relate directly to myeloma progression." (PMID 25623282, 2015). "Taken together, various studies have demonstrated SDC1 as a potential biomarker for multiple myeloma." (PMID 26293675, 2015). "Mulitple molecules such as ADAM-10, ADAM-17, MMP-7, MMP-9, MMP-14, and bFGF/FGF2 increase SDC1 shedding in multiple myeloma as well as breast and colon cancers." (PMID 26293675, 2015). "In the same study, myeloma patients responding to chemotherapy treatment showed reduced SDC1 levels." (PMID 26293675, 2015). "In a cohort of Korean patients diagnosed with multiple myeloma, soluble SDC1 levels correlated with disease stage and characteristics." (PMID 26293675, 2015). "Further studies showed that soluble SDC1 levels were elevated in the sera of multiple myeloma patients treated with high-dose chemotherapy and subsequent autologous transplantation." (PMID 26293675, 2015). "It is present in the nucleus of myeloma cells, and amount of nuclear syndecan-1 is reduced upon elevation of heparanase expression." (PMID 26420915, 2015). "Specifically, Syndecan-1 (CD138), a heparan-sulfate proteoglycan is attracting interests as it is highly expressed and shed by myeloma plasma-cells." (PMID 26025441, 2015). "A recent study showed that SDC1 is present in the nucleus of myeloma tumor cells where it activates gene transcription." (PMID 26293675, 2015). "When SDC1 expression was analyzed in normal bone marrow or bone marrow from multiple myeloma and B-cell lymphoma patients, SDC1 was found to be expressed predominantly in normal and neoplastic plasma cells." (PMID 26293675, 2015). "Several studies have shown higher levels of soluble SDC1 in multiple myeloma patients compared to healthy controls." (PMID 26293675, 2015). "GLVGLIFAV is an SDC1-specific peptide that is recognized by cytotoxic T lymphocytes generated ex vivo using an HLA-A2-specific SDC1 epitope against multiple myeloma cells." (PMID 26293675, 2015). "In another study, the extent to which soluble SDC1 levels fell from presentation to the plateau phase represented a prognostic predictor in multiple myeloma patients." (PMID 26293675, 2015). "Results of in vivo studies showed that SST0001 effectively inhibited myeloma growth and diminished heparanase-induced shedding of SDC1." (PMID 26293675, 2015). "The antitumor action of chemically modified heparins has been shown to inhibit myeloma growth and angiogenesis via disruption of the heparanase/syndecan-1 axis, and our data strongly confirm the usefulness of this therapeutic approach." (PMID 25386176, 2014). "In multiple myeloma, SDC-1 promotes endothelial cells proliferation and survival by modulating VEGF–VEGFR-2 signaling pathway." (PMID 24551591, 2014). "Soluble SDC-1 is present at high levels in the serum of myeloma patients, promoting the growth of myeloma tumors in vivo." (PMID 24551591, 2014). "Roneparstat also diminishes heparanase-induced shedding of syndecan-1, which is known to be a potent promoter of myeloma growth." (PMID 25105093, 2014). "The mechanism of heparanase aggressive phenotype priming is in part due to synergy with the heparan sulfate proteoglycan syndecan-1 to create a niche within the bone marrow microenvironment, further driving myeloma growth and dissemination." (PMID 25386176, 2014).
myeloma (continued). "Studies have pinpointed soluble SDC-1 ectodomain in the serum of lung cancer patients, Hodgkin’s lymphoma patients, and myeloma patients as well as within the ECM of the myeloma microenvironment." (PMID 24551591, 2014). "Upregulation of heparanase expression or exogenous addition of recombinant heparanase to myeloma cells stimulates SDC-1 expression and shedding." (PMID 24551591, 2014). "A most interesting candidate for further investigation includes CSGALNACT1 which encodes a protein involved in the synthesis of chondroitin sulphate, a component of Syndecan-1 (CD138) involved in myeloma pathogenesis." (PMID 24376673, 2013). "Accordingly, the levels of shed syndecan-1 in serum correlate with a less favorable prognosis in lung cancer, lymphoma, myeloma, hepatocellular carcinoma, and glioma." (PMID 24392351, 2013). "“Squeezing” this sponge by shedding of the heparan-sulfates from the syndecan-1 core protein, e.g. by heparanase produced by myeloma cells or the bone marrow environment, can liberate these growth factors and promotes angiogenesis." (PMID 24386263, 2013). "For example, it has been shown that myeloma cells decrease OPG availability by internalizing it through binding to glycosaminoglycan side chains of surface syndecan-1 and degradation to lysosomes, thereby regulating its inhibitory effect on RANKL." (PMID 23862137, 2013). "We show here that syndecan-1 positive (CD138+) myeloma cells secrete nanovesicles that are taken up by osteoblast-like cells and increase the secretion of IL-11 in the recipient cells." (PMID 26082068, 2012). "Previous reports suggested that in myeloma cells, HS chains regulate the targeting of syndecan-1 to uropod, a specialized domain on the cell surface." (PMID 22396758, 2012). "In patients affected by MM syndecan-1, a heparan sulphate proteoglycan is overexpressed by myeloma cells in the BM and peripheral blood." (PMID 22649466, 2012). "Results from studies using several in-vivo model systems support the notion that enzymatic activities responsible for syndecan-1 modification are valid targets for myeloma therapy." (PMID 23908791, 2011). "B-B4 is a murine IgG1 mAb targeting syndecan-1 that was originally developed for multiple myeloma by Wijdenes and colleagues." (PMID 22214534, 2011). "Upon upregulation of heparanase expression or following addition of recombinant heparanase to myeloma cells, the nuclear localization of syndecan-1 drops dramatically as revealed by confocal microscopy, western blotting and quantification by ELISA." (PMID 19305494, 2009). "Myeloma cells, like normal mature plasma cells express syndecan-1 (CD 138) cell surface antigen that is limited to terminally differentiated plasma cells originating of B lymphocyte lineage." (PMID 19152712, 2009). "By confocal microscopy, western blotting and ELISA assay we demonstrate that when heparanase expression is increased in a human myeloma cell line, the level of syndecan-1 in the nucleus decreases dramatically." (PMID 19305494, 2009). "Syndecan-1 is particularly abundant in multiple myeloma, where an emerging role for heparanase has recently been shown." (PMID 18545691, 2008). "In multiple myeloma, Sdc1 mediates ligand binding and signalling through the hepatocyte growth factor (HGF) receptor tyrosine kinase c-met, resulting in increased cancer cell proliferation." (PMID 17244359, 2007). "Altered expression of syndecan-1 has been documented in many human carcinomas, lymphomas and in multiple myeloma; in multiple myeloma syndecan-1 has been proposed for clinical use as a prognostic marker." (PMID 16620374, 2006). "CD138 (syndecan-1) expression is significantly elevated on the surface of myeloma cells." (PMID 40977723, 2025). "Furthermore, heparanase‐enhanced shedding of SDC1 by myeloma cells has been shown to promote endothelial invasion and angiogenesis." (PMID 41039734, 2025). "A CAR-T for the treatment of multiple myeloma against syndecan-1 (CD138) has been developed." (PMID 38727261, 2024).
myeloma (continued). "However, recent work demonstrated that multiple myeloma cells expressing junctional adhesion molecule C exhibit low surface expression of syndecan-1 in murine bone marrow, challenging the notion that all multiple myeloma cells express syndecan-1 uniformly." (PMID 38912739, 2024). "SDC1 is a maker of long-lived plasma cells and myeloma pathogenesis." (PMID 38380329, 2024). "Purification of myeloma cells is often performed by this method using anti-CD138 monoclonal antibodies conjugated to magnetic beads, since plasma cells, in contrast to other cells in the bone marrow, express high levels of the proteoglycan CD138 (syndecan-1)." (PMID 39493694, 2024). "Myeloma cell adhesion to BMSCs or extracellular matrix components by expression of adhesion molecules such as Syndecan-1, intercellular adhesion molecule 1 (ICAM-1) or vascular cell adhesion protein 1 (VCAM-1) prevent apoptosis, resulting in cell-adhesion driven drug resistance." (PMID 37744361, 2023). "Of these, the most specific marker for myeloma cells is CD138 (Syndecan-1)." (PMID 35886877, 2022). "Moreover, in head and neck squamous cell carcinoma the cells with the higher levels of Sdc-1 are less migratory and invasive, while the increase in soluble Sdc-1 favors migration and angiogenesis in myeloma." (PMID 35155241, 2022). "In addition, it has been shown that B-lymphoid and myeloma plasma cells expressing syndecan-1 bind to collagen type I in the malignant HSC niche." (PMID 34838648, 2022). "Syndecan-1 is well characterized as a marker for multiple myeloma." (PMID 34838648, 2022). "In addition, SDC1 has been the gold-standard surface marker to detect multiple myeloma (MM) cells for decades." (PMID 36388159, 2022). "In agreement, in myeloma Sdc-1 functions as an inhibitory factor of apoptosis." (PMID 35155241, 2022). "It is noteworthy that the soluble form of syndecan-1 promotes the growth of myeloma in vivo." (PMID 33842343, 2021). "Increased levels of shed syndecan-1 have been reported in some cancers such as breast and prostate and have been correlated with poor prognosis in patients with lung cancer and myeloma." (PMID 33669066, 2021). "Syndecan-1 has also been used as a target for multiple myeloma treatment." (PMID 33669066, 2021). "Given its relevance to myeloma progression, syndecan-1-directed antibody—toxin conjugates are being tested in clinical and preclinical trials, and may have future relevance to some carcinomas." (PMID 33921767, 2021). "In addition to CD19 antigen, which expresses commonly in multitude of B-cell malignancies and likely in stem cell-like subpopulation of multiple myeloma (MM), CD138 (syndecan-1) has gained our attention." (PMID 34337077, 2021). "Moreover, Sdc-1 facilitates angiogenesis of multiple myeloma endothelial cells by modulating VEGF/VEGFR-2 signaling, providing an additional mechanistic link." (PMID 34066023, 2021). "Furthermore, chemotherapy was found to potentially promote HGF/c-Met/IL-11 activation via SDC-1 shedding, exacerbating bone destruction in the setting of myeloma." (PMID 35118073, 2021). "In addition, the activation of the Wnt/β-catenin cascade in multiple myeloma is also promoted by HS chains of SDC1, leading to cancer cells proliferation." (PMID 33494442, 2021). "This strong expression has also led to considerable interest in SDC1's role in multiple myeloma." (PMID 33561383, 2021). "Syndecan-1 is highly expressed in multiple myeloma and is now considered as an important target." (PMID 33921767, 2021). "As an example, in multiple myeloma cells, SDC1 was shown to interact with HGF via HS chains, promoting enhanced activation of Met and consequent activation of the PI3K/protein kinase B and RAS-Raf MAPK pathways, which are related to cell proliferation and survival." (PMID 33494442, 2021). "Interestingly, many ongoing clinical trials are exploring the safety and efficacy of targeting syndecan-1 in multiple myeloma." (PMID 32983743, 2020).
myeloma (continued). "Syndecan-1 or CD138 is a heparan sulfate proteoglycan and a surface marker of myeloma cells." (PMID 33634031, 2020). "For instance, the interaction of SDC4 and RSPO3 was shown to regulate WNT/planar cell polarity (PCP) signaling during Xenopus gastrulation by a process that requires clathrin-mediated endocytosis, and SDC1 was shown to promote signaling in multiple myeloma by presenting WNTs and RSPOs." (PMID 32432544, 2020). "Additionally, heparanase stimulates the expression of MMP-9 via ERK signaling, promoting shedding of syndecan-1 proteoglycan (CD138) from the myeloma cell surface." (PMID 31963505, 2020). "In addition, cleavage of the HS side chains of syndecan-1 augments the shedding of this proteoglycan from the surface of myeloma cells, leading to a more aggressive disease." (PMID 33585253, 2020). "For example, in multiple myeloma, high HPSE expression is linked to poor prognosis, and contributes to disease pathogenesis by inducing Sdc-1 shedding from the tumor cell membrane, which promotes sequestering of shed Sdc-1 bound growth factors in the tumor microenvironment." (PMID 32477959, 2020). "In fact, stimulation of Sdc1 shedding by heparanase enhances Met signaling in myeloma cells." (PMID 32453780, 2020). "Soluble syndecan-1 has been shown to promote myeloma tumor growth in vivo." (PMID 33634031, 2020). "CD138, also known as Syndecan-1, has also been recently investigated as a potential target for antibody-conjugated drug therapies for multiple myeloma as well as in a wide variety of cancer types, including bladder cancer and triple-negative breast cancer due to overexpression in these malignancies." (PMID 33138841, 2020). "In addition, they express cell-specific molecules that can often be considered as immunophenotypical markers such as syndecan-1/CD138, a plasma cell marker characteristic of multiple myeloma cells." (PMID 31266187, 2019). "For example, SDC1 suppresses TRAIL-mediated apoptosis in multiple myeloma cells." (PMID 30197623, 2018). "SDC1 is overexpressed in endothelial cells derived from patients with multiple myeloma." (PMID 30197623, 2018). "For example, several studies found that syndecan-1 may promote myeloma tumor growth in vivo, but inhibit growth of both carcinoma and myeloma cells in vitro." (PMID 30135409, 2018). "Similarly, SDC1 that is expressed in multiple myeloma has been shown to activate WNT signaling by two mechanisms." (PMID 30197623, 2018). "In addition, progression of multiple myeloma is positively correlated with Sdc-1 expression on malignant plasma cells." (PMID 28293067, 2017). "Syndecan-1 has also been proposed as target in myeloma therapy." (PMID 26378057, 2015). "Moreover, high SDC1 expression was detected in all multiple myeloma cases examined, whereas all B-cell lymphomas were completely negative." (PMID 26293675, 2015). "Moreover, shed syndecan-1 is able to deliver growth factors to other cells, as it was shown for syndecan-1 originating from multiple myeloma cells, which is released in the medium and is taken up by the surrounding stromal cells." (PMID 26420915, 2015). "Shed syndecan-1 can be incorporated into the bone marrow extracellular matrix, which supports myeloma or may remain as a soluble component within the bone marrow plasma." (PMID 25686828, 2015). "Heparanase accelerates MMP-9 mediated shedding of syndecan-1 in both myeloma and breast cancer." (PMID 26420915, 2015). "Furthermore, some secreted HSGPs, such as syndecan-1 and glypican-1, are increased in a variety of malignancies such as thyroid, pancreatic cancer, breast cancer and myeloma." (PMID 26488476, 2015). "Findings from these studies indicate that soluble SDC1 levels may be a prognostic tool in multiple myeloma patients for diagnosis, prognosis, and treatment response." (PMID 26293675, 2015).
myeloma (continued). "Earlier, lack of CD44-expression in EBV-positive or EBV-negative BL cell lines, up-regulation of serglycin and CD44 in EBV+ BL cells, down-regulation of syndecan-1/CD138 in EBV-infected multiple myeloma cells and fibronectin and collagen in multiple myeloma patients have already been reported." (PMID 26527314, 2015). "Similarly, high level of soluble syndecan-1 in serum indicates poor prognosis for patients with multiple myeloma and lung cancer." (PMID 25147801, 2014). "Similarly, heparanase has been demonstrated to regulate the expression of syndecan-1 in multiple myeloma cells." (PMID 25105093, 2014). "Moreover, EGF-family ligands are essential for multiple myeloma cell growth via binding with HSPGs and especially with SDC-1, which is abundantly expressed in this malignancy." (PMID 24551591, 2014). "Syndecan-1 translocates to the cell nucleus of various tumor cells, including malignant mesothelioma, fibrosarcoma, neuroblastoma, breast- and lung adenocarcinoma, and multiple myeloma." (PMID 24392351, 2013). "Thus, in tumors with elevated syndecan-1 level such as multiple myeloma or breast adenocarcinoma, applicable approaches comprise anti-syndecan-1 antibodies, knockdown of syndecan-1, competitive inhibitors or anti-angiogenic agents." (PMID 24392351, 2013). "Cleavage and shedding of the SDC1 ectodomain is found in multiple myeloma." (PMID 24373193, 2013). "For instance, as tumours become more aggressive, heparanase activity is enhanced in myeloma, lymphomas or breast cancer, increasing both the number of exosomes released and the amount of syndecan-1, VEGF and HGF molecules exposed on their surface, making them more available for detection." (PMID 24223259, 2013). "Syndecan-1/CD138 is a transmembrane proteoglycan expressed by most myeloma plasma cells." (PMID 22629140, 2012). "Moreover, syndecan-1 binds HGF on the surface of myeloma cells bringing HGF in close proximity of its receptor c-Met." (PMID 19187270, 2009). "Using confocal microscopy we noted that syndecan-1 was localized within the nucleus of CAG myeloma cells expressing low levels of heparanase (HPSE-low cells) but it not present within the nucleus of CAG cells expressing high levels of heparanase (HPSE-high cells)." (PMID 19305494, 2009). "Although it is unclear whether increased heparan sulfation on syndecan-1 specifically mediates this effect, these findings provide significant insight into the multicellular roles of HSPGs and their modifications in regulating myeloma." (PMID 38912739, 2024). "Notably, myeloma growth in vivo is stimulated by the soluble form of syndecan-1." (PMID 38540127, 2024). "Given the importance of syndecan-1 HSPG in several cancer types, including breast, colon, lung, and myeloma, the development of new HS-binding antibodies and antibody derivatives is important for therapy and for understanding the functional roles of HS sulfation in syndecan-1." (PMID 37046595, 2023). "Also unique to the myeloma cells compared to carcinoma or endothelial cells is that IGF-1R in the pre-assembled Sdc1-coupled ternary receptor complex is constitutively active; it is not dependent on cell adhesion or IGF-1, although exogenous IGF1 stimulates increased levels of IGF-1R activation." (PMID 34778093, 2021). "Overexpression of syndecan-1 is reported in many hematological and solid tumors such as multiple myeloma, non-Hodgkin's lymphoma, and breast, bladder, pancreatic, lung, ovarian, endometrial, and hepatocellular carcinoma, and its expression may affect the prognosis of those cancers." (PMID 32983743, 2020). "The resistance might have occurred because the chemotherapy used in the treatment of myeloma stimulated the synthesis and shedding of syndecan-1, which led to the accumulation of high levels of syndecan-1, thus enhancing relapse and promoting tumor progression." (PMID 32983743, 2020).